NUDT21 (nudix hydrolase 21)
Diseases named in the same sentence as NUDT21 in open-access papers (continued):
Sharing a sentence is not in itself a finding about the gene and the disease.
gastric cancer (continued). "In this study, 70 gastric cancer tissues and 70 normal gastric tissues from patients were collected and immunohistochemistry (IHC) assay was performed to determine the protein level of NUDT21." (PMID 34660260, 2021). "Therefore, NUDT21 played an oncogenic role in human gastric cancer cells." (PMID 34660260, 2021). "Therefore, SGPP2 mediated the tumor promoting role of NUDT21 in gastric cancer cells." (PMID 34660260, 2021). "Therefore, Bcl-2 and CCNE1 might contribute to the tumor promoting role of the NUDT21/SGPP2 pathway in gastric cancer cells." (PMID 34660260, 2021). "In these 70 gastric cancer patients, their clinicopathological features (including age, gender, tumor size, lymph node metastasis, histology grade and clinical stage) were collected and the correlation between NUDT21 expression levels and the clinicopathological features were analyzed." (PMID 34660260, 2021). "Therefore, NUDT21 positively regulated the expression of SGPP2 in human gastric cancer cells." (PMID 34660260, 2021). "NUDT21 could possibly be perceived as a novel target for gastric cancer therapy." (PMID 34660260, 2021). "NUDT21 could be considered as a novel potential target for gastric cancer therapy." (PMID 34660260, 2021). "Nevertheless, the role of NUDT21 in human gastric cancer cells remains unclear." (PMID 34660260, 2021). "published that NUDT21 promoted cell proliferation, colony formation, cell migration and invasion through modulating SGPP2 in human gastric cancer." (PMID 36816917, 2023). "It has been reported that Nudix hydrolase 21 promotes tumor growth and metastasis through modulating SGPP2 in gastric cancer." (PMID 34956309, 2021). "The mRNA levels of NUDT21 in normal gastric cell line GES-1 and gastric cancer cell lines AGS, BGC-823, SGC-7901, HGC-27, MKN-28 were examined by RT-qPCR." (PMID 34660260, 2021). "Gastric cancer tissues from patients with distant metastasis showed an elevated NUDT21 level compared with the tissues from patients without distant metastasis." (PMID 34660260, 2021).
glioma (6 papers, 2017 to 2024). A benign or malignant brain and spinal cord tumor that arises from glial cells (astrocytes, oligodendrocytes, ependymal cells). "However, more efforts should be directed toward clarifying the functions of this gene, and additional proteins encoded by NUDT21 may be essential for glioma survival and malignancy." (PMID 29311812, 2017). "For the first time, we show that NUDT21 can promote glioma cell proliferation by activating NF-κB signaling." (PMID 29311812, 2017). "U87MG cells were transfected with shNUDT21 to further elucidate the physiological role of NUDT21 in glioma cell growth." (PMID 29311812, 2017). "In the present study, driven by the fact that NUDT21 is a promising candidate from gene screening, we sought to examine its potential roles in glioma incidence, tumor growth and MES transdifferentiation." (PMID 29311812, 2017). "Here, we report that NUDT21 expression was upregulated in human glioma tissues and that NUDT21 promoted glioma cell proliferation, likely through the NF-κB signaling pathway." (PMID 29311812, 2017). "Cell proliferation assay indicated that NFKBIZ silencing could reverse the effect of NUDT21 in human glioma, and NF-κB nuclear translocation induced by LPS could also reverse the anticancer effect of NUDT21 knockdown." (PMID 29311812, 2017). "NUDT21 is a newly discovered gene that could be of great significance in glioma malignancy." (PMID 29311812, 2017). "NUDT21 plays a pivotal role in 3′-end processing and might be indispensable for elucidating the fundamental mechanisms regarding regulating alternative poly(A) site selection, thus controlling glioma malignancy." (PMID 29311812, 2017). "Furthermore, expression of CPSF5/CFIm25/NUDT21 was reported to be down-regulated in the lungs of patients with idiopathic pulmonary fibrosis (IPF) or mice with pulmonary fibrosis, in HEK293 cells, and in low/high grade glioma cells, causing a global shortening of 3′UTRs." (PMID 34829789, 2021).
cervical cancer (5 papers, 2020 to 2025). A primary or metastatic malignant neoplasm involving the cervix. "This work is expected to provide new insights into the mechanism by which HPV16 E6/E7 regulate ABHD2/NUDT21 through miR-4454 to better understand the malignant transformation of cervical cancer." (PMID 32816024, 2020). "In follow-up experiments, we will further explore the specific roles of ABHD2/NUDT21 in the development of HPV16-positive cervical cancer and its related mechanisms." (PMID 32816024, 2020). "In conclusion, miR-4454 was overexpressed in HPV16 positive cervical cancer cells, and HPV16 E6/E7 may affect cancer cell invasion and migration via miR-4454/ABHD2/NUDT21 axis in cervical cancer cells." (PMID 32816024, 2020). "Our data also suggested that NUDT21 is negatively correlated to miR-4454, and knockdown of NUDT21 increased the invasion and migration of HPV16 E6/E7-positive CaSki cell compared with HPV16-negative C33A cell, indicating an effect in promoting the development of human cervical cancer." (PMID 32816024, 2020).
leukemia (4 papers, 2019 to 2024). A malignant (clonal) hematologic disorder, involving hematopoietic stem cells and characterized by the presence of primitive or atypical myeloid or lymphoid cells in the bone marrow and the blood. "have reported that both Bcl-2 and CCNE1 were positively regulated by NUDT21 and they mediated the promoting role of NUDT21 in human leukemia cells." (PMID 34660260, 2021). "In chronic myelocytic leukemia patients NUDT21 is highly expressed, and depletion of NUDT21 in leukemia cells inhibits growth and proliferation, possibly through inhibition of the extracellular signal-regulated kinase (ERK) signalling pathway." (PMID 32560344, 2020). "In hematologic malignancy, silencing NUDT21 inhibits proliferation and promotes apoptosis of human K562 leukemia cells through regulation of p-ERK expression." (PMID 31695759, 2019). "NUDT21 played oncogenic roles in human pancreatic ductal adenocarcinoma cells and leukemia cells." (PMID 34660260, 2021).
liver cancer (4 papers, 2020 to 2022). An epithelial or non-epithelial malignant neoplasm that arises from the liver. "Recently, we have reported that CFIm25 (encoded by Nudt21) exerted suppressive effect on liver cancer cells." (PMID 33648552, 2021). "Besides, NUDT21 participated in the occurrence of liver cancer." (PMID 34082777, 2021). "The modulation of NUDT21 expression induced global APA alteration, and the knockdown of NUDT21 increased the usage of the proximal polyadenylation site in serval tumor suppressor genes and promoted cell proliferation, metastasis, and tumorigenesis in liver cancer." (PMID 32153636, 2020).
pulmonary fibrosis (4 papers, 2020 to 2025). Chronic progressive interstitial lung disorder characterized by the replacement of the lung tissue by connective tissue, leading to progressive dyspnea, respiratory failure, or right heart failure. "Importantly, mice with Nudt21 deletion in Col1a1 expressing cells aggravated bleomycin-induced pulmonary fibrosis." (PMID 40738116, 2025). "A final example is found in idiopathic pulmonary fibrosis development, where transforming growth factor beta 1 (TGFB1) mediates the down-regulation of NUDT21 via induction of miR-203 resulting in APA shortening." (PMID 32560344, 2020).
viral infection (4 papers, 2017 to 2026). "Furthermore, despite advances in understanding mRNA APA events in activated macrophages and recent discoveries regarding the role of CPSF6 during viral infections, substantial gaps exist in our knowledge of APA regulators such as Nudt21 in macrophage-mediated inflammatory diseases." (PMID 39537902, 2024).
acute lymphoblastic leukemia (3 papers, 2024 to 2026). Leukemia with an acute onset, characterized by the presence of lymphoblasts in the bone marrow and the peripheral blood. "The 3’ end processing factor NUDT21 limits expression of CD19 in B-cell progenitor acute lymphoblastic leukemia (B-ALL) cells by regulating CD19 mRNA polyadenylation." (PMID 38416782, 2024). "Screening CD19+ expression in B cell precursor acute lymphoblastic leukemia (BCP-ALL) revealed the contrasting functions of Zinc Finger Protein 143 and Nudix Hydrolase 21 (NUDT21)." (PMID 39538305, 2024).
chronic myelocytic leukemia (3 papers, 2020 to 2024). "Zhang found that NUDT21 was upregulated in chronic myelogenous leukemia, and the inactivation of NUDT21 inhibited proliferation and promoted apoptosis of K562 cells." (PMID 38349866, 2024). "The NUDT21 mRNA levels were much higher in patients with primary chronic myelocytic leukemia compared with normal control." (PMID 34660260, 2021).
colon cancer (3 papers, 2019 to 2026). "It was found that high expressions of NUDT21 (HR= 0.57, P = 0.023), GNB1 (HR=0.028, P=0.026), and CLINT1 (HR=0.6, P=0.043) were associated with better overall survival for colon cancer patients." (PMID 30881993, 2019). "NUDT21, CPSF3, CSTF2, and MTPAP were overexpressed while PCF11 and PABPN1 were suppressed in colon cancer tissues." (PMID 32153636, 2020). "Taken together, NUDT21, GNB1, CLINT1, and COL1A2 were considered as core genes with a close relationship to colon cancer." (PMID 30881993, 2019). "this study suggested that NUDT21, GNB1, CLINT1, and COL1A2 might be the core genes for colon cancer that play an important role in the development and prognosis of IIA stage colon cancer." (PMID 30881993, 2019). "Moreover, further deeply investigated molecular mechanism of NUDT21, COL1A2, GNB1, CLINT1, and colon cancer is necessary; it is also the limitation of this study." (PMID 30881993, 2019). "In conclusion, this study showed that NUDT21, GNB1, CLINT1, and COL1A2 might be the potential core genes that play an important role in the development and prognosis in IIA stage colon cancer." (PMID 30881993, 2019). "Finally, NUDT21, COL1A2, GNB1, and CLINT1 closely related to the overall survival of colon cancer were selected as core genes." (PMID 30881993, 2019). "Finally, NUDT21, GNB1, CLINT1, and COL1A2 core gene were selected due to their correlation with the prognosis of IIA stage colon cancer." (PMID 30881993, 2019). "And we found that NUDT21, GNB1, CLINT1, and COL1A2 might be the potential core genes that play an important role in the development and prognosis in IIA stage colon cancer." (PMID 30881993, 2019).
colorectal cancer (3 papers, 2025 to 2026). A primary or metastatic malignant neoplasm that affects the colon or rectum. "Notably, SRSF3, CPSF3, FIP1L1, CTR9, NUDT21, and CSTF2, among others, were found to exhibit a more significant contribution to the differential 3′-UTR gene expression in colorectal cancer." (PMID 40702779, 2025).
esophageal squamous cell carcinoma (3 papers, 2025). Esophageal squamous cell carcinoma (ESCC) is a type of esophageal carcinoma (EC) that can affect any part of the esophagus, but is usually located in the upper or middle third. "Additionally, AARS1 was identified as the primary lactyltransferase responsible for catalyzing the lactylation of nudix hydrolase 21 (NUDT21) in esophageal squamous cell carcinoma (ESCC) cell lines (KYSE30 cells)." (PMID 41008630, 2025).
Intellectual disability (3 papers, 2015 to 2020). "Altogether, these results provide important in vivo and human-specific evidence that reduced NUDT21 expression can cause intellectual disability." (PMID 32319885, 2020). "Altogether, these results show that disruption of NUDT21-regulated APA events in the brain can cause intellectual disability." (PMID 32319885, 2020). "We previously showed that NUDT21-spanning copy-number variations (CNVs) are associated with intellectual disability." (PMID 32319885, 2020). "Alongside our previous discovery that patients with NUDT21-spanning deletions have intellectual disability and gnomAD data that NUDT21 is a highly constrained gene, our results provide strong evidence that partial loss of NUDT21 function causes intellectual disability." (PMID 32319885, 2020). "For instance, highly conserved binding sites of NUDT21 were found to be significantly (p < 0.05) involved in ‘Neurodevelopmental abnormality’, and literature proposes that NUDT21 is a major player in causing intellectual disability and neuropsychiatric diseases among humans." (PMID 31888461, 2019). "We focused on learning and memory assays because intellectual disability is the most pronounced and consistent symptom seen in patients with NUDT21-spanning CNVs." (PMID 32319885, 2020). "Combining results from our previous work with data from the Decipher database, we have identified nine individuals with NUDT21-spanning duplications that have intellectual disability, and two patients with deletions that have both intellectual disability and seizures." (PMID 32319885, 2020). "The observations that individuals with NUDT21-spanning CNVs have intellectual disability (ID) and that Nudt21+/- mice have learning deficits provide strong evidence that NUDT21 loss of function causes disease, but do not reveal the molecular pathology." (PMID 32319885, 2020). "Because a relatively small reduction in CFIm25 protein was sufficient to cause deficits, these data suggest that individuals with missense variants in NUDT21 that affect its function may also have intellectual disability." (PMID 32319885, 2020). "In addition to intellectual disability, the patients with NUDT21-spanning deletions had seizures." (PMID 32319885, 2020).
non-small cell lung carcinoma (3 papers, 2021 to 2025). A group of at least three distinct histological types of lung cancer, including non-small cell squamous cell carcinoma, adenocarcinoma, and large cell carcinoma. "NUDT21 has recently been confirmed as a HIF1α responsive target, accounting for hypoxia-induced loss of NUDT21 in non-small cell lung cancer cells." (PMID 35671866, 2022).
pancreatic ductal adenocarcinoma (3 papers, 2021 to 2024). An infiltrating adenocarcinoma that arises from the epithelial cells of the pancreas. "Zheng found that NUDT21 was a valuable marker in the prognosis of pancreatic ductal adenocarcinoma and can promote tumor proliferation and inhibit apoptosis through EIF2 signaling." (PMID 38349866, 2024). "Pancreatic ductal adenocarcinoma tissues showed elevated NUDT21 compared with normal tissues, and high level of NUDT21 predicted poor prognosis of patients with pancreatic ductal adenocarcinoma." (PMID 34660260, 2021). "NUDT21 played an oncogenic role in human pancreatic ductal adenocarcinoma cells, promoting both cell proliferation and metastasis." (PMID 34660260, 2021).
cognitive defects (2 papers, 2020 to 2023). "We found that the Nud21+/- mice were not hyperactive, thus validating the conditioned fear results by showing they are not confounded by hyperactivity, and showing that partial loss of Nudt21 function does cause cognitive defects." (PMID 32319885, 2020). "However, the cognitive impairment induced by sevoflurane was alleviated by overexpressed NUDT21, suggesting that NUDT21 protected against sevoflurane-caused cognitive impairment." (PMID 37077345, 2023). "Morris water maze test results revealed that overexpression of NUDT21 improved sevoflurane-induced cognitive impairment." (PMID 37077345, 2023). "Therefore, to clarify the role of abnormally expressed NUDT21 in sevoflurane-induced neurological damage, the cognitive impairment was detected using the Morris water maze test." (PMID 37077345, 2023). "Taken together, NUDT21 improved sevoflurane-induced cognitive impairment in rats." (PMID 37077345, 2023).
osteosarcoma (2 papers, 2020 to 2024). A usually aggressive malignant bone-forming mesenchymal neoplasm, predominantly affecting adolescents and young adults. "In different organ tumor studies, Zhu demonstrated that reducing the protein level of NUDT21 in osteosarcoma tissue can inhibit cell proliferation and promote cell apoptosis." (PMID 38349866, 2024).
prostate carcinoma (2 papers, 2025). A carcinoma that arises from epithelial cells of the prostate gland. "Moreover, unmethylated NUDT21 has been implicated in cuproptosis insensitivity in prostate cancer by promoting copper export and inhibiting docosahexaenoic acid biosynthesis." (PMID 40425546, 2025). "NUDT21 overexpression acts as a key regulator of alternative polyadenylation (APA) and exhibits oncogenic properties in prostate cancer, with its unmethylated 3′UTR shortening identified as a novel mechanism underlying enzalutamide resistance." (PMID 40406488, 2025).
Sepsis (2 papers, 2024 to 2025). Sepsis is defined as life-threatening organ dysfunction caused by a dysregulated host response to infection. "Furthermore, given the broad role of macrophages in inflammatory disorders, future studies should investigate the function of NUDT21 and APA in other disease contexts, such as sepsis and acute kidney injury." (PMID 41282183, 2025). "Elevated levels of NUDT21 mRNA were observed in inflamed tissues from patients with inflammatory bowel disease (IBD), psoriasis, rheumatoid arthritis (RA), and sepsis." (PMID 39537902, 2024).
B-cell acute lymphoblastic leukemia (1 paper, 2023). A neoplasm of lymphoblasts committed to the B-cell lineage, typically composed of small to medium-sized blast cells. "They foung that NUDT21 limits CD19 levels through alternative mRNA polyad xsenylation in B cell acute lymphoblastic leukemia.Nudt21 has been reported to both prohibit and promote tumor progression.In many cancers, NUDT21 acts as a tumor suppressor." (PMID 36816917, 2023).
colitis (1 paper, 2024). Inflammation of the colon. "By utilizing myeloid-specific Nudt21-deficient mice, we revealed a protective effect of Nudt21 depletion against colitis and severe hyperinflammation, primarily through diminished production of proinflammatory cytokines." (PMID 39537902, 2024). "The reduction in colitis severity in Nudt21-cKO mice underscores the critical role of Nudt21 in modulating macrophage-mediated inflammatory responses." (PMID 39537902, 2024). "To determine the functional impact of Nudt21 deficiency on macrophages during inflammatory disease progression, we subjected WT and Nudt21-cKO mice to a 3% dextran sulfate sodium (DSS) protocol for five days to induce colitis." (PMID 39537902, 2024). "Consequently, we generated mice with lineage-specific deletion of Nudt21 in macrophages (Nudt21fl/fl LysMCre, synonymous with Nudt21-cKO) and documented a reduction in inflammation in two murine disease models—colitis and HLH—characterized by decreased proinflammatory cytokine production." (PMID 39537902, 2024).
endometrial cancer (1 paper, 2024). Primary or metastatic malignant neoplasm involving the endometrium (mucous membrane that lines the endometrial cavity). "CTL was found to be negatively correlated with NUDT21 in endometrial cancer." (PMID 38349866, 2024).